RNU6-131P (RNA, U6 small nuclear 131, pseudogene)
Gene: Small nuclear RNA gene on chromosome 17 (44,135,883 to 44,135,989, reverse strand). Ensembl gene ENSG00000212446.
Homologues: Orthologues: chimpanzee U6 (86% identical), pig U6 (76% identical), mouse Gm22883 (73% identical), rat LOC120095359 (73% identical), pig U6 (72% identical), pig U6 (65% identical). Paralogues in human: RNU6-16P (82% identical), RNU6-21P (82% identical), RNU6-480P (82% identical), RNU6-1 (81% identical), RNU6-144P (81% identical), RNU6-2 (81% identical), RNU6-38P (81% identical), RNU6-39P (81% identical), RNU6-3P (81% identical), RNU6-4P (81% identical), RNU6-5P (81% identical), RNU6-6P (81% identical), and 1284 more.